Y_RNA (Y RNA )
Gene: Miscellaneous RNA gene on chromosome 3 (179,097,731 to 179,097,840, forward strand). Ensembl gene ENSG00000200616.
Homologues: Orthologues: chimpanzee Y_RNA (96% identical), macaque Y_RNA (94% identical). Paralogues in human: Y_RNA (79% identical), RNY1 (78% identical), Y_RNA (78% identical), Y_RNA (77% identical), Y_RNA (76% identical), RNY1P1 (75% identical), RNY1P11 (75% identical), RNY1P5 (75% identical), Y_RNA (75% identical), RNY1P8 (75% identical), RNY1P2 (74% identical), Y_RNA (74% identical), and 92 more.